IL6 (interleukin 6)
Diseases named in the same sentence as IL6 in open-access papers (continued):
Sharing a sentence is not in itself a finding about the gene and the disease.
cystitis (continued). "In rodent models of CYP-induced cystitis, functional and pharmacological studies suggest pERK and pAKT may induce pCREB, mTOR, type 1 collagen, and cytokine expression, including IL-6." (PMID 35528149, 2022). "In mouse models of bladder infection with uropathogenic E. coli, transcription of the il6 gene was found to be very highly upregulated at 2 hr and moderately upregulated at 24 hr after infection, with response kinetics varying between mouse strains, suggesting genetic control." (PMID 25807366, 2015). "Increased serum IL-6 and IL-8 in chronic cystitis could indicate an adaptive immune response after previous bladder infections." (PMID 24098552, 2013). "Increased serum IL-6 and IL-8 in chronic cystitis might indicate an adaptive immune response after previous bladder infections." (PMID 24146927, 2013). "A comparison with acute cystitis samples showed that the levels of IL-6 and IL-8 were lower in ABU." (PMID 22140570, 2011). "Interestingly, a previous study of a cohort of elderly females and males reported that urinary levels of CXCL1, IL-8, and IL-6 were significantly elevated in patients with acute cystitis compared with patients with asymptomatic bacteriuria (ASB) or negative controls." (PMID 38331474, 2024). "Thus, RA may decrease IL6 production to improve cystitis symptoms including shortening of micturition interval." (PMID 37463180, 2023). "Further, in the urine of women with IC, rats with experimentally induced cystitis, and cats with FIC, higher IL-6 production was detected." (PMID 38026670, 2023). "Prevention by oral gavage of imatinib reduced VEGFaa, VEGFab, BDNF, IL-6 and CCL2 mRNA, and VEGF and IL-6 protein expression in the LP and whole bladder, respectively, in mice with acute CYP-induced cystitis." (PMID 35528149, 2022). "We assessed the therapeutic effects of Tt-SOD on HCl-induced cystitis by detecting the serum levels of certain inflammatory factors (TNF-α, IL-1β and IL-6) by specific Elisa kits." (PMID 34783980, 2022). "We examined the inflammatory mediators, BDNF, NGF, VEGF, IL-6, and CCL2, and signaling kinases, pERK and pAKT, in the urinary bladder and LP, due to their established involvement in CYP-induced cystitis." (PMID 35528149, 2022). "Here, we examine inflammatory mediators (e.g., NGF, BDNF, VEGF, CCL2, IL-6) previously shown to increase expression and exhibit functional effects in micturition pathways in rodent models of CYP-induced cystitis." (PMID 35528149, 2022). "Effect of pregabalin (30 mg kg-1, s.c) on IL-6, KC and TNFα concentration in bladder and plasmatic level in cyclophosphamide (CYP)-induced cystitis mice model." (PMID 30863309, 2019). "This was confirmed by examination of the pro-inflammatory factors showing that interleukin (IL)-1α, IL-6 and tumor necrosis factor (TNF)α levels in the urinary bladder were increased with cystitis." (PMID 25486122, 2014). "Previous studies of urine chemokine levels have mainly focused on IL-6 and CXCL-8 during episodes of symptomatic cystitis." (PMID 20016852, 2009). "Our results showed that the expression levels of TNF-α, IL-6, and IL-1β were enhanced in E. coli-induced cystitis rat, and knockdown of TPRG1 suppressed the inflammatory response in E. coli-induced cystitis rat through down-regulation of TNF-α, IL-6, and IL-1β." (PMID 34998360, 2022). "Cytokines and chemokines such as TNF-α, IL-6, and IL-8 have a crucial role in the bladder inflammation, and the increased levels of these cytokines have been reported in IC/BPS patients and the experimental cystitis model." (PMID 33133219, 2020). "Our previous study revealed that the protein level of IL-6 in cyclophosphamide induced cystitis in rats was significantly decreased at day 4 but had no significant change at day 8 after LESW treatment." (PMID 31561455, 2019).
cystitis (continued). "As well, there were trends toward higher serum IL-5 and IL-6 levels in mice that would develop chronic CFT073 cystitis, but, unlike with UTI89-infected mice, the differences were not statistically significant." (PMID 30543708, 2018). "Elevated levels of interleukin-6 (IL-6), keratinocyte cytokine (KC/CXCL1), and granulocyte colony-stimulating factor (G-CSF) in the serum of C57BL/6 mice prior to the second infection predicted the development of chronic cystitis." (PMID 26999218, 2016). "Elevated levels of interleukin-6 (IL-6), keratinocyte cytokine (KC/CXCL1), and granulocyte colony-stimulating factor (G-CSF) in the serum of C57BL/6J mice prior to the second infection predicted the development of chronic cystitis." (PMID 25569799, 2015). "Based on earlier studies, the levels of the pro-inflammatory cytokine interleukin- (IL-6) and the pro-inflammatory chemokine stromal-cell derived factor-1 (SDF-1) were increased in the urine and uroepithelial cells in the case of experimentally induced cystitis in rats." (PMID 36851436, 2023). "UTI studies in human and mice have reported several cytokine/chemokine responses to urinary infection and their role in UTI including IL-6, IL-8, and IL-1 response during human UTI; the expression of IL-6 and IL-1α has also been detected in animal models of cystitis." (PMID 37051302, 2023). "Imatinib prevention by oral gavage (250 mg/kg) significantly (p ≤ 0.05) decreased VEGFaa, VEGFab, IL-6, CCL2 and BDNF LP mRNA but did not affect NGF LP mRNA in mice with 4 h CYP-induced cystitis (1.6–6.5-fold)." (PMID 35528149, 2022). "Imatinib treatment via transurethral bladder infusion did not significantly affect CCL2, IL-6, BDNF, NGF, VEGFaa or VEGFab LP mRNA or urinary bladder protein expression in female mice with 4 h CYP cystitis." (PMID 35528149, 2022). "They found that the serum and urinary levels of IL-6 and IL-8 were significantly higher in patients with APN than in those with cystitis and no UTI." (PMID 29134126, 2017).
HCMV infection (39 papers, 2010 to 2026). "We next proceeded to characterize the effects of HCMV infection on the secretion of IL-6 and IL-8, two inflammatory cytokines often associated with a senescent phenotype." (PMID 38459109, 2024). "In contrast, the low levels of IL-6 associated with the rs10499563C allele would disfavour the occurrence of CMV infection." (PMID 32450795, 2020). "When compared to the IL-6 rs10499563T/T genotype, the rs10499563T/C was associated with a lower risk of CMV infection as the genotype was significantly (p < 0.001) less frequent in the CMV+ group (14%) than the CMV- group (70%)." (PMID 32450795, 2020). "The IL-6 rs10499563T > C polymorphism was significantly associated with lower risk of CMV infection." (PMID 32450795, 2020). "In addition to CRP, the proinflammatory cytokines TNF and interleukin-6 (IL-6) are secreted in response to HCMV infection and are independently associated with mortality due to CVD." (PMID 29752343, 2018). "This distinct response appears to be mediated by IL-6, underscoring the unique cellular mechanisms at play in renal epithelial cells in the context of HCMV infection." (PMID 38459109, 2024). "Human cytomegalovirus (HCMV) infection also induces the production of proinflammatory cytokines in inflammatory cells, including IL-1β, IL-6, IL-12, TNF-α, interferon-α/β and IFN-γ." (PMID 39459871, 2024). "Analogously, it has been found that TPRG1L upregulated IL-6 expression via NF-κB pathway in human cytomegalovirus infection." (PMID 36401185, 2022). "Here, we report that hCMV infection strongly induces EC IL-11, and document its temporal expression dynamics compared to the induction of IL-6." (PMID 29807687, 2018). "Inflammatory factors including Tumor Necrosis Factor (TNF)-alpha, interleukin-6 (IL-6), and nitric oxide synthase 2 are produced by M1 macrophages following HCMV infection." (PMID 30081496, 2018). "The HCMV infection of HepG2 and primary human hepatocyte cells results in the activation of the IL-6/JAK/STAT3 pathway, which enhances the HepG2 tumor sphere formation and the transformation of primary human hepatocyte cells." (PMID 32201498, 2018). "HCMV infection and especially pUS28 enhance tumor inflammation, for example, by induced production of IL-6, RANTES, MCP-1, and fraktaline." (PMID 30081496, 2018). "We detail temporal EC IL-11 translation and protein secretion dynamics in response to hCMV infection, and reveal distinct differences compared to EC IL-6." (PMID 29807687, 2018). "We found that the knockdown of CD147 expression in HFF cells decreased the activation of IFNB1 and interferon-stimulated ISG15 gene expression induced by HCMV infection, as well as expression of the NF-κB downstream genes IL-6 and TNF-α." (PMID 29194430, 2017). "HCMV infection induces IL-6 secretion most probably through the expression of the viral-encoded chemokine receptor US28 and the activation of the IL6/STAT3 signaling pathway." (PMID 23592985, 2013). "HCMV infection induces pro-inflammatory cytokine responses in inflammatory cells, with production of interleukin (IL)-1β, IL-6, IL-12, tumour necrosis factor (TNF)-α, interferon (IFN)-α/β, IFN-γ and prostaglandin E2 (PGE2)." (PMID 23722135, 2013). "IL-6 expression in response to HCMV infection was similar to that observed for MD2 expression, peaking at 1 hour post incubation with HCMV." (PMID 22970235, 2012). "IL-6 mRNA expression is up-regulated by HCMV infection and increased IL-6 levels are a critical factor involved in inflammation and carcinogenesis, especially in liver." (PMID 22032643, 2011). "Interestingly, IL-12 has been shown to be required for expansion of adaptive NK cells in response to murine cytomegalovirus infection, while a stimulatory effect of TNFα and potential inhibition of cytotoxic activity of NK cells by IL-6 has been reported." (PMID 40473838, 2025).
HCMV infection (continued). "Consequently, we propose a model wherein IL-6 plays an essential role in initiating and promoting paracrine senescence in response to HCMV infection." (PMID 38459109, 2024). "Importantly, TCZ did not interfere with IL-6 release in the culture supernatants upon HCMV infection, implying that this inhibitor disrupts IL-6 mediated induction of paracrine effects while leaving the extracellular release of IL-6 unaffected." (PMID 38459109, 2024). "Since HCMV reactivation in the TME could lead to increased IL-6 production, these data suggest that active HCMV infection in the TME may also drive the expansion of highly suppressive CD4+TNFR2+ Tregs." (PMID 33808294, 2021). "In addition, CMV infection induces the pro-inflammatory cytokine IL-6, which then triggers ECs to release CCL-2, which recruits more monocytes and T-cells into the vessel wall thereby exacerbating local inflammation, and thus atherogenesis." (PMID 29409508, 2018). "The most important protein targets based on its degree from the C-T-P-D network were TNF, MAPK1, MAPK3, IL6, IL1B, AKT1 and CASP3 and the most important pathways associated with these protein targets were “Pathways in cancer”, “IL-17 signaling pathway”, and “Human cytomegalovirus infection”." (PMID 36591238, 2022). "Similarly, in primary human hepatocytes and HepG2 cells the IL-6/STAT3 axis is also activated upon HCMV infection and could favor sustained cellular transformation." (PMID 30081496, 2018). "In fact, IL-6 and TNF-α levels in HCMV infected patients’sera are significantly higher, and the high level of IL-6 may indicate a higher risk of HCMV infection, thus being beneficial for early diagnose of HCMV infection." (PMID 25088288, 2014). "In contrast, DOs responded to HCMV infection by secreting both proinflammatory cytokines and chemokines (e.g., CXCL10, MIP-1α, MIP-1β, and IL-6) and through the release of the type III IFN IFN-λ2." (PMID 35975985, 2022). "In patients with active HCMV infection, i.e. group 1 and group 2, the mean concentrations of CRP, IL6, IL10 and MCP1 were found to be quite similar but significantly varied from group 3 patients." (PMID 35538132, 2022). "TNF-α, IL-6, and IL-1β at 24–28 weeks of gestation were significantly higher in women with GDM and HCMV infection than inthe other groups (all P < 0.01)." (PMID 35186501, 2022). "The polarisation and activation of monocytes due to HCMV infection or reactivation leads to high systemic levels of inflammatory cytokines, particularly tumour necrosis factor (TNF) and IL-6, as well as diminished immune function." (PMID 33808294, 2021). "HCMV infection disrupts the IL-6-induced phosphorylation of STAT3 and inhibition of a subset of IL-6/STAT3-regulated gene expression, including SOCS3." (PMID 32201498, 2018). "UVB-inactivated HCMV infection failed to stimulate IL-6 production in all three cell lines, confirming that its induction requires active replication." (PMID 38459109, 2024). "BMX protein expression also increased in response to HCMV infection without IL-6 treatment; therefore, our results identify BMX, a regulator of GBM stemness via STAT3 activation, as a novel target of HCMV." (PMID 25549333, 2014). "IL-6 mRNA expression is upregulated by HCMV infection in the absence of de novo expression of viral genes." (PMID 22032643, 2011). "Although some reports indicate that HCMV infection and/or viral proteins modulate STAT3 intracellular localization, IL-6 signaling, and NF-kB activation, altogether, HCMV participates to shape the tumorous environment and thereby could favor the development and spread of the tumor." (PMID 30081496, 2018). "HCMV infection of PHH and HepG2 cells results in activation of the IL-6-JAK-STAT3 pathway which results in the transformation of PHH cells and enhanced HepG2 tumorsphere formation raising the possibility that HCMV infection might be involved in the genesis of hepatocellular carcinoma." (PMID 26199948, 2015).
HCMV infection (continued). "Indeed, our transcriptome analysis revealed a specific enrichment of the IL-6/JAK-STAT3 signaling pathway in HCMV-infected RPTECs, which led us to demonstrate that exposure to the IL-6R inhibitor TCZ can significantly disrupt the paracrine inflammatory loop elicited by HCMV infection." (PMID 38459109, 2024). "However, acute treatment with recombinant IL-6 has not been shown to induce monocyte permissiveness for HCMV infection alone, implying that either the effects of IL-6 are chronic long-term effects or, in fact, may be working in concert with other factors." (PMID 28993776, 2017). "We found that IL-6 and TNF-α levels in the cells infected with HCMV were significantly higher than in the mock infected cells, but curcumin significantly reduced the secretion of the two cytokines, suggesting that curcumin may be an effective anti-HCMV infection agent." (PMID 25088288, 2014). "Chronic HCMV infection could potentially promote these important oncogenic signaling pathways since HCMV infection expresses a chemokine receptor US28, which has oncogenic potential and has been shown to signal through the NF-kB pathway and activate downstream COX-2, STAT-3 and IL-6 expression." (PMID 21429243, 2010).
Headache (39 papers, 2012 to 2026). Cephalgia, or pain sensed in various parts of the head, not confined to the area of distribution of any nerve. "Decreased CD4 T cells independently predicted COVID-associated headaches, with elevated IL-6 levels noted in the dominant-headache group (p = 0.040)." (PMID 39274228, 2024). "There is a direct relationship between headache and inflammation caused by COVID‐19 and high levels of IL‐6 as a marker of pain." (PMID 35385200, 2022). "According to the ROC curve cutoff values they suggested that VAS >70 severity, >9 h duration, >5 headache days, and IL-6 >43 pg/ml levels can be diagnostic for COVID-19 headache." (PMID 35911910, 2022). "Considerable clinical evidence suggests that IL-6 and IL-8 are mainly involved in pain and in mediating neuroinflammation associated with migraine headaches." (PMID 34685736, 2021). "CRP, TNF-α and IL-6 have been positively associated with migraine headache, a usual symptom of PMS22." (PMID 31624297, 2019). "IL-6 is also suggested to be linked with headache, especially migraine attacks." (PMID 35498555, 2022). "Pro-inflammatory cytokines, including interleukin 1, tumor necrosis factor alpha, and interleukin 6, are known to activate brain nerve endings, resulting in the pain experienced as headaches." (PMID 41249949, 2025). "Increased serum IL-6 levels were not only related to headache chronification but also with headache severity and drug unresponsiveness in COVID-19 headache which is also a secondary headache." (PMID 37940864, 2023). "Supporting this, higher serum levels of interleukin-6, angiotensin, ACE 2 as well as of lymphocytes have been detected in patients with long COVID infection with a predisposing headache biology." (PMID 37897023, 2023). "Several pro-inflammatory cytokines such as IL-6 and IL-1β are also nociceptive in the trigeminovascular system and take a part in the headache development." (PMID 37940864, 2023). "For example, headaches are associated with elevated Tumor Necrosis Factor-α (TNF-α), Interleukin-10 (IL-10), Interleukin-1β (IL-1β), Interleukin-6 (IL-6), and Interferon-α (IFN-α) levels." (PMID 35053845, 2022). "IL-6 presumably gives rise to headaches in NMOSD and disrupts the CNS system, since it facilitates the activation of TH17 cells." (PMID 35498555, 2022). "In that study, the subgroup of patients with bilateral headache (77 out of 83 patients with headache), had higher levels of IL-6 than patients with unilateral headache." (PMID 35915417, 2022). "In glyceryl trinitrate-induced experimental headache studies, activation of NFκβ, IL1β, IL-6 and NLRP3 inflammasome are shown within perivascular macrophages in the dura mater and in microglial cells nearby trigeminal sensory neurons in the brainstem." (PMID 34384355, 2021). "In the trigeminal system, IL-6 can activate perivascular trigeminal nociceptors in the dura mater and induce headache in behavioral experimental studies." (PMID 34384355, 2021). "In the headache group, IL-6 levels were lower at the ER (22.9 (57.5) vs. 57.0 (78.6) pg/mL; p = 0.036) and more stable during hospitalisation." (PMID 33146036, 2020). "We observed lower levels of IL-6 at the ER in the headache group, a finding that cannot be explained by different stages of the disease between groups." (PMID 33146036, 2020). "The reduction in headache with improvements in gait, visual symptoms, and MRI lesions, along with a modest improvement in cognition, indicate that IL-6 inhibitors may confer broad neurological benefits." (PMID 40717732, 2025). "Nerve blocks administered weekly have reduced IL-6 in general chronic pain-like headache conditions, suggesting that similar markers could be reduced in FM patients." (PMID 39897251, 2025). "Increased levels of the circulating inflammatory and/or nociceptive molecules like HMGB1, NLRP3, and IL-6 may play a role in the potential induction of the trigeminal system and manifestation of headache secondary to SARS-CoV-2 infection." (PMID 34384355, 2021).